MGRN1 (mahogunin ring finger 1)
Diseases named in the same sentence as MGRN1 in open-access papers (continued):
Sharing a sentence is not in itself a finding about the gene and the disease.
melanoma (continued). "This suggests that MGRN1 may modulate the malignant phenotype of melanoma cells." (PMID 33019669, 2020). "However, a higher rate of melanoma or other malignancies has not yet been reported for mahoganoid mice, and, with a rate of ~1.7% non-synonymous substitutions, MGRN1 mutations are not frequent in human melanoma according to the TCGA database." (PMID 33019669, 2020). "Therefore, MGRN1 appears an important determinant of the malignant phenotype of melanoma." (PMID 33019669, 2020). "Therefore, MGRN1 expression might be an important determinant of the phenotype and aggressiveness of human melanoma cells." (PMID 33019669, 2020). "Therefore, the potential roles of MGRN1 in melanomagenesis, on one hand, and in the clinical course of the disease, on the other, remain largely unexplored, thus preventing the exploitation of this protein as a potentially useful therapeutic target and/or melanoma biomarker." (PMID 35892921, 2022). "To test this possibility, we knocked down MGRN1 expression in B16-F10 melanoma cells by CRISPR/Cas9 and selected two independent Mgrn1-KO clones for further analysis." (PMID 33019669, 2020). "Therefore, MGRN1 might be an important phenotypic determinant of melanoma cells." (PMID 33019669, 2020). "Nevertheless, these findings again suggested a negative correlation between high MGRN1 expression and disease outcome, further underscoring its potential use as a melanoma biomarker." (PMID 35892921, 2022). "A consistent decrease in AO labeling was obtained for melanocytes and melanoma cells lacking MGRN1 upon CRISPR-Cas9 knockdown." (PMID 34921635, 2021). "Therefore, the simple MGRN1-MLANA-PMEL-TYRP1 combination of biomarkers complemented TNM staging prognostic accuracy and pointed to the dysregulation of immunological responses and genomic stability as determinants of a melanoma outcome." (PMID 40004203, 2025). "Analysis of MGRN1-KO mouse melanocytes and melanoma cells showed that lack of MGRN1 leads to cell cycle defects and to a more differentiated, less aggressive phenotype, with increased adhesion to various matrices, decreased motility and high genomic instability." (PMID 33019669, 2020). "We obtained consistent results in MNT-1 human melanoma cells, characterized by melanosome biogenesis and protein or gene expression profiles comparable to normal human melanocytes, indicating that the pigmentation stimulatory effect of MGRN1 downregulation was not restricted to mouse cells." (PMID 34921635, 2021). "MGRN1-KO cells presented significantly higher levels of γ-H2AX labeling compared with control cells, pointing to a higher burden of DSBs in human melanoma cells lacking MGRN1." (PMID 35892921, 2022).
breast carcinoma (3 papers, 2016 to 2020). "In keeping with this possibility, a study on osteosarcoma patients showed recurrent amplifications of the 16p13 region where MGRN1 is located, and another investigation reported hypomethylation of CpG sites in MGRN1 in blood cells from breast cancer patients." (PMID 33019669, 2020). "Previous findings for cg06418238 in RPTOR, cg00736299 in MGRN1, and cg27466532 in RAPSN that were recently reported to be associated with breast cancer risk were not replicated by our study." (PMID 31101124, 2019). "An analysis published after the systematic review reported CpG sites cg06418238 in RPTOR, cg00736299 in MGRN1, and cg27466532 in RAPSN to be more commonly hypomethylated in breast cancer cases, although these associations were not replicated by the Melbourne Collaborative Cohort Study (MCCS)." (PMID 31101124, 2019).
Obesity (2 papers, 2022 to 2025). Accumulation of substantial excess body fat. "Mgrn1- and Atrn-null mutant mice share strikingly similar phenotypes, including a dark coat color due to the loss of a subapical band of pheomelanin on individual hairs and an elevated basal metabolic rate that confers resistance to diet-induced obesity." (PMID 41178558, 2025).
osteosarcoma (2 papers, 2020). A usually aggressive malignant bone-forming mesenchymal neoplasm, predominantly affecting adolescents and young adults. "In support of this notion, the MGRN1 locus has been reported to be amplified in osteosarcomas and, according to information provided in the Human Protein Atlas, most cancer types, except gliomas, showed a moderate to strong cytoplasmic staining of the MGRN1 protein." (PMID 32075127, 2020).
ovarian carcinoma (2 papers, 2020 to 2021). A malignant neoplasm originating from the surface ovarian epithelium. "MGRN1 mRNA expression was also strongly associated with EGR1 mRNA expression in the ovarian cancer population (P<0.01)." (PMID 34268111, 2021). "Furthermore, we also investigated the possible role and mechanism of decreased MGRN1 expression in ovarian cancer cells in the response to cisplatin in vitro." (PMID 34268111, 2021). "Moreover, a statistically significant correlation of low MGRN1 expression and higher survival probability was also observed for two prevalent types of cancer, namely lung squamous cell carcinoma (p = 0.0049) and ovarian cancer (p = 0.0029) according to the TCGA database." (PMID 33019669, 2020).
cutaneous melanoma (1 paper, 2022). A primary melanoma arising from atypical melanocytes in the skin. "This analysis indicated that cutaneous melanoma (SKCM) is one of the cancers with a higher expression of MGRN1." (PMID 35892921, 2022). "This was confirmed by the estimation of MGRN1 expression in a cohort of nevi and skin melanoma specimens." (PMID 35892921, 2022).
endometriosis (1 paper, 2025). The growth of functional endometrial tissue in anatomic sites outside the uterine body. "Some studies have reported that MGRN1 is related to tumor cell adhesion and migration, which could make it a valuable new biomarker for the development of endometriosis." (PMID 40140093, 2025). "Therefore, MGRN1 should also be given significant attention in the context of endometriosis." (PMID 40140093, 2025).
male infertility (1 paper, 2016). The inability of the male to effect fertilization of an ovum after a specified period of unprotected intercourse. "Likewise, the gene MGRN1 is widely expressed in the male reproductive system, and recent studies have shown that MGRN1 knockout in mice results in male infertility, with disruption of hormones secretion and impaired sperm motility." (PMID 27842509, 2016).
neuroblastoma (1 paper, 2025). Neuroblastoma (NB) is the most common solid, extracranial childhood tumor. "Fluorescently labeled ATRN and MGRN1 colocalize in HEK293T cells and interactions have been observed by co-immunoprecipitation (co-IP) experiments conducted in Neuro2A neuroblastoma cells." (PMID 41178558, 2025).
pancreatic cancer (1 paper, 2020). "As opposite to GLI3, the transmembrane protein MEGF8, which interacts with mahogunin ring finger-1 (MGRN1) for the ubiquitination and degradation of Smo, is not correlated with pancreatic cancer." (PMID 33266496, 2020).
scrapie (1 paper, 2013). A fatal disease of the nervous system in sheep and goats, characterized by pruritus, debility, and locomotor incoordination. "This indicates that absence of MGRN1 does not accelerate the pathogenesis of scrapie, but does not distinguish whether RML prions cause disease by disrupting MGRN1 function or act independent of MGRN1." (PMID 23383230, 2013).
serous ovarian cancer (1 paper, 2021). "In our previous study, reduced representation bisulfite sequencing (RRBS) analysis showed that the promoter region of the Mahogunin Ring Finger 1 (MGRN1) gene had abnormal hypermethylation in high-grade serous ovarian cancer (HGSOC) patients with platinum resistance." (PMID 34268111, 2021). "In this study, we explored the relationship between hypermethylation of the Mahogunin Ring Finger 1 (MGRN1) gene promoter and primary chemoresistance and clinical outcomes in high-grade serous ovarian cancer (HGSOC) patients." (PMID 34268111, 2021).
sterility (1 paper, 2025). "A deficiency in MGRN1 in mice leads to decreased hormone levels, reduced sperm concentration, and sterility, negatively impacting mitochondrial health." (PMID 40649876, 2025).
tumor (6 papers, 2020 to 2025). "We found that high expression of MGRN1 was associated with a higher tumor thickness at diagnosis, with a strong statistical significance (p = 0.0012)." (PMID 35892921, 2022). "After adjusting for other prognostic factors (age, stage, grade and tumor residual size), low MGRN1 expression was also significantly associated with shorter OS (P=0.01), demonstrating that MGRN1 expression was an independent predictor of poorer clinical outcomes in HGSOC patients." (PMID 34268111, 2021). "Moreover, a higher prevalence of MGRN1 mutations is found in other tumor types such as endometroid cancers, with ~6% of these tumors in the TCGA cohort harboring non-synonymous MGRN1 mutations." (PMID 33019669, 2020). "RT-qPCR was used to determine the mRNA levels of MGRN1 in the tumor tissues from 41 platinum-resistant HGSOC patients and 55 platinum-sensitive HGSOC patients." (PMID 34268111, 2021). "The molecular bases of the association of MGRN1, PMEL, MLANA, and TYRP1 expression within the tumor and patient survival remain speculative." (PMID 40004203, 2025). "Interestingly, a recent study identified MGRN1 in an 8-gene signature predicting the response to immunotherapy in MM, further supporting its role in modulating the immune microenvironment of the tumor." (PMID 40004203, 2025). "Moreover, we identified three differentially methylated regions within the MGRN1, MIR596, and TAPBP genes that have been linked to neuronal aging, tumor growth, and immune functions." (PMID 38414347, 2024). "Tumor growth was monitored, and results showed that mice implanted with XBP1s-OE A549 cells developed significantly larger tumors, whereas MGRN1-knockdown cells failed to maintain their resistance to copper-induced cell death." (PMID 40253387, 2025). "However, the role of MGRN1 in tumorigenesis, tumor progression, and drug responses is not currently well understood." (PMID 34268111, 2021).
cancer (4 papers, 2020 to 2022). A tumor composed of atypical neoplastic, often pleomorphic cells that invade other tissues. "Therefore, the possibility that MGRN1 might behave as a cancer susceptibility gene deserves further analysis." (PMID 33019669, 2020). "Similar to TAL, it is currently unknown whether a deregulated expression of MGRN1 significantly contributes to the expression and oncogenic properties of TSG101 in cancer." (PMID 32075127, 2020). "However, there is no study of the role of MGRN1 in chemotherapy resistance in cancer patients to date." (PMID 34268111, 2021). "However, in spite of its relationship with components of the cytoskeleton, no study on the regulation by MGRN1 of cell shape and movement of normal or cancer cells has yet been reported." (PMID 33019669, 2020).
neurodegenerative disease (1 paper, 2017). A disorder of the central nervous system characterized by gradual and progressive loss of neural tissue and neurologic function. "Recent studies have strongly suggested potential neurobiological roles of MGRN1 in NDDs and neurodegenerative diseases." (PMID 28579943, 2017). "Growing number of findings indicate the role of MGRN1 in neurodegenerative diseases." (PMID 28579943, 2017).
MGRN1 also shares sentences with these, for which no sentence is quoted: acute myeloid leukemia (1 paper); Alzheimer disease (1); Cyanosis (1); glioma (1); hemorrhage (1); lung squamous cell carcinoma (1); neurodevelopmental disorder (1); neurological disorders (1); Parkinson disease (1); transmissible spongiform encephalopathy (1).